KLHL38 (kelch like family member 38)
Synonyms: C8orfK36
Tractability: Small molecule: it belongs to a druggable protein family.
Gene: Protein-coding gene on chromosome 8 (123,644,442 to 123,653,801, reverse strand). Ensembl gene ENSG00000175946.
Subcellular location (Human Protein Atlas): Nucleoplasm; Cytosol
Gene Ontology:
Molecular function: protein binding; ubiquitin-like ligase-substrate adaptor activity
Biological process: proteasome-mediated ubiquitin-dependent protein catabolic process
Cellular component: Cul3-RING ubiquitin ligase complex; cytoplasm
Genetic constraint (gnomAD): Loss-of-function variants: 40 observed, 41.18 expected, observed/expected ratio (o/e) 0.97, 90% interval 0.75 to 1.26. The upper end of that interval is the gene's LOEUF score, 1.26, which puts it in group 5 of 6, group 1 being the genes least tolerant of losing a copy. Missense variants: 799 observed, 774.72 expected, observed/expected ratio (o/e) 1.03, 90% interval 0.97 to 1.09. Synonymous variants: 321 observed, 317.46 expected, observed/expected ratio (o/e) 1.01, 90% interval 0.92 to 1.11.
Homologues: Orthologues: chimpanzee KLHL38 (98% identical), macaque KLHL38 (98% identical), rabbit KLHL38 (88% identical), dog KLHL38 (87% identical), pig KLHL38 (84% identical), mouse Klhl38 (84% identical), rat Klhl38 (84% identical), guinea pig KLHL38 (84% identical), tropical clawed frog klhl38 (66% identical), zebrafish klhl38a (56% identical), zebrafish klhl38b (52% identical). Paralogues in human: KLHL24 (31% identical), KLHL21 (29% identical), KLHL30 (28% identical), KLHL6 (28% identical), KLHL28 (28% identical), KLHL29 (28% identical), KLHL35 (27% identical), KLHL20 (27% identical), KLHL12 (26% identical), KLHL2 (26% identical), KLHL17 (26% identical), KLHL3 (26% identical), and 42 more.
Diseases named in the same sentence as KLHL38 in open-access papers:
KLHL38 is named in the same sentence as 8 diseases in open-access papers, as found by Europe PMC text mining. Sharing a sentence is not in itself a finding about the gene and the disease. The quoted sentences say what the papers report.
non-small cell lung carcinoma (2 papers, 2021 to 2023). A group of at least three distinct histological types of lung cancer, including non-small cell squamous cell carcinoma, adenocarcinoma, and large cell carcinoma. "For example, in non-small cell lung cancer, KLHL38 overexpression promotes PTEN ubiquitination and activates Akt signaling, thereby promoting cell proliferation, migration, and invasion." (PMID 36611207, 2023).
lung carcinoma (1 paper, 2021). "Western blotting confirmed that KLHL38 levels were higher in 14 of the 16 lung cancer tissues analyzed than in the matched normal tissues." (PMID 34050138, 2021). "Collectively, these findings demonstrate that KLHL38 promotes the migration and invasion of lung cancer cells." (PMID 34050138, 2021). "Results of co-immunoprecipitation experiments revealed that KLHL38 directly interacts with PTEN in lung cancer cells." (PMID 34050138, 2021). "Overall, 43 matched pairs of clinical lung cancer and normal tissue samples were selected for RNA extraction, and KLHL38 levels were measured." (PMID 34050138, 2021). "As KLHL38 expression was correlated with lymph node metastasis, we speculated that KLHL38 could be related to the migration and invasion of lung cancer cells." (PMID 34050138, 2021). "Moreover, immunohistochemical results showed that KLHL38 was overexpressed in clinical lung cancer tissues, whereas in normal bronchi and alveoli, KLHL38 was minimally expressed." (PMID 34050138, 2021). "However, the role of KLHL38 in lung cancer is currently unclear." (PMID 34050138, 2021). "However, the qRT-PCR analysis indicated that PTEN expression was unchanged regardless of KLHL38 expression in lung cancer cell lines, indicating that the interaction between KLHL38 and PTEN may occur at the protein rather than mRNA level." (PMID 34050138, 2021).
lymph node metastasis (1 paper, 2021). "KLHL38 levels positively correlated with tumor size, lymph node metastasis, and pathological tumor-node-metastasis stage (all P < 0.001)." (PMID 34050138, 2021).
cancer (2 papers, 2018 to 2021). A tumor composed of atypical neoplastic, often pleomorphic cells that invade other tissues. "KLHL38 levels were significantly higher in cancers than in matched normal tissues (single sample paired t-test, P = 0.000)." (PMID 34050138, 2021). "Only KLHL29, KLHL38, and KLHL22 had hazard ratios or inverse hazard ratios >2 in the same direction with three cancer types." (PMID 30647843, 2018).
adenocarcinoma (1 paper, 2021). A common cancer characterized by the presence of malignant glandular cells. "In both A549 and H1299 adenocarcinoma cells and in SK-MES-1 squamous cells, Moreover, KLHL38 expression was significantly associated with the promotion of migration and invasion." (PMID 34050138, 2021). "In vitro experiments using the adenocarcinoma cell lines A549 and H1299 and the squamous cell line, SK-MES-1 demonstrated that KLHL38 promotes migration and invasion by upregulating RhoA and MMP9 and downregulating E-cadherin." (PMID 34050138, 2021).
heart diseases (1 paper, 2019). "Other genes have not been implicated in heart diseases (ADPRHL1, KLHL38, SH3BGR)." (PMID 31641117, 2019).
tumor (1 paper, 2021). "Changes in KLHL38 expression in these cells positively affected the xenograft tumor volume and weight." (PMID 34050138, 2021). "Our statistical study found that the cut-off value for KLHL38 and tumor size was exactly the referred value, which also suggests clinical significance." (PMID 34050138, 2021). "KLHL38 expression was evaluated in tumor and adjacent normal tissues from 241 patients with NSCLC using immunohistochemistry and real-time PCR, and its association with clinicopathological parameters was analyzed." (PMID 34050138, 2021). "The effect of KLHL38 expression on tumor size was evaluated as a reflection of cell proliferation." (PMID 34050138, 2021). "This study demonstrated that KLHL38 localizes in the cytoplasm and nucleus, and that its expression level correlates with a range of clinicopathological parameters in NSCLC, including tumor size, lymph node metastasis, and pathological tumor-node-metastasis stage." (PMID 34050138, 2021).
KLHL38 also shares sentences with these, for which no sentence is quoted: lung adenocarcinoma (1 paper).